H2BC14 (H2B clustered histone 14)
Description:
Core component of nucleosome. Nucleosomes wrap and compact DNA into chromatin, limiting DNA accessibility to the cellular machineries which require DNA as a template. Histones thereby play a central role in transcription regulation, DNA repair, DNA replication and chromosomal stability. DNA accessibility is regulated via a complex set of post-translational modifications of histones, also called histone code, and nucleosome remodeling.
Synonyms: H2B/e; H2BFE; HIST1H2BM; dJ160A22.3
Tractability: PROTAC: UniProt records ubiquitination sites on it; ubiquitination databases record sites on it.
Gene: Protein-coding gene on chromosome 6 (27,815,022 to 27,815,489, forward strand). Ensembl gene ENSG00000273703.
Subcellular location: Nucleus; Chromosome
Subcellular location (Human Protein Atlas): Nucleoplasm; Cytosol
Pathways (Reactome):
Gene expression (Transcription): B-WICH complex positively regulates rRNA expression; DNA methylation; ERCC6 (CSB) and EHMT2 (G9a) positively regulate rRNA expression; MLL4 and MLL3 complexes regulate expression of PPARG target genes in adipogenesis and hepatic steatosis; NoRC negatively regulates rRNA expression; PRC2 methylates histones and DNA; RNA Polymerase I Promoter Escape; RNA Polymerase I Promoter Opening; RUNX1 regulates genes involved in megakaryocyte differentiation and platelet function; RUNX1 regulates transcription of genes involved in differentiation of HSCs; Regulation of endogenous retroelements by KRAB-ZFP proteins; Regulation of endogenous retroelements by Piwi-interacting RNAs (piRNAs); Regulation of endogenous retroelements by the Human Silencing Hub (HUSH) complex; SIRT1 negatively regulates rRNA expression; Transcriptional regulation by small RNAs
Chromatin organization: CHD1 and CHD2 subfamily; CHD6, CHD7, CHD8, CHD9 subfamily; ChAHP complex assembly; HATs acetylate histones; HDACs deacetylate histones; Interaction of NuRD complexes with transcription factors; NuRD complex assembly
DNA Repair: Cleavage of the damaged purine; Cleavage of the damaged pyrimidine; Nonhomologous End-Joining (NHEJ); Processing of DNA double-strand break ends; Recognition and association of DNA glycosylase with site containing an affected purine; Recognition and association of DNA glycosylase with site containing an affected pyrimidine; Recruitment and ATM-mediated phosphorylation of repair and signaling proteins at DNA double strand breaks
Cell Cycle: Condensation of Prophase Chromosomes; Deposition of new CENPA-containing nucleosomes at the centromere; G2/M DNA damage checkpoint; Inhibition of DNA recombination at telomere; Packaging Of Telomere Ends
Developmental Biology: Activation of anterior HOX genes in hindbrain development during early embryogenesis; Chromatin modifications during the maternal to zygotic transition (MZT); Replacement of protamines by nucleosomes in the male pronucleus; Transcriptional regulation of granulopoiesis
Disease: Defective pyroptosis; Dengue Virus-Host Interactions
and 18 more pathways
Gene Ontology:
Molecular function: DNA binding; structural constituent of chromatin; protein heterodimerization activity
Biological process: antibacterial humoral response; antimicrobial humoral immune response mediated by antimicrobial peptide; chromatin organization; innate immune response in mucosa; nucleosome assembly
Cellular component: extracellular exosome; nucleus; nucleoplasm; nucleosome; chromosome
Genetic constraint (gnomAD): Loss-of-function variants: 17 observed, 6.64 expected, observed/expected ratio (o/e) 2.56. That is too few expected variants to judge how well the gene tolerates losing a copy. Missense variants: 235 observed, 176.71 expected, observed/expected ratio (o/e) 1.33, 90% interval 1.2 to 1.48. Synonymous variants: 131 observed, 74.03 expected, observed/expected ratio (o/e) 1.77, 90% interval 1.53 to 1.96.
Homologues: Orthologues: chimpanzee H2BC14 (100% identical), macaque H2BC14 (98% identical), mouse H2bc9 (97% identical). Paralogues in human: H2BC10 (97% identical), H2BC15 (97% identical), H2BC3 (97% identical), H2BC4 (97% identical), H2BC5 (97% identical), H2BC6 (97% identical), H2BC7 (97% identical), H2BC8 (97% identical), H2BC12 (96% identical), H2BC21 (96% identical), H2BC9 (96% identical), H2BC11 (95% identical), and 9 more.
Diseases named in the same sentence as H2BC14 in open-access papers:
H2BC14 is named in the same sentence as 8 diseases in open-access papers, as found by Europe PMC text mining. Sharing a sentence is not in itself a finding about the gene and the disease. The quoted sentences say what the papers report.
cancer (5 papers, 2017 to 2022). A tumor composed of atypical neoplastic, often pleomorphic cells that invade other tissues. "Meanwhile, only a few studies on H2BC14 and H4C11 in cancer have been reported." (PMID 36407085, 2022).
H2BC14 also shares sentences with these, for which no sentence is quoted: breast carcinoma (2 papers); tumor (2); chronic myeloid leukemia (1); infection (1); mucositis (1); prediabetes (1); systemic lupus erythematosus (1).